CDK1 (cyclin dependent kinase 1)
Diseases named in the same sentence as CDK1 in open-access papers (continued):
Sharing a sentence is not in itself a finding about the gene and the disease.
cervical cancer (43 papers, 2008 to 2025). A primary or metastatic malignant neoplasm involving the cervix. "CDK1 may play a significant role in regulating the genetic network associated with cervical cancer occurrence, development, and metastasis." (PMID 35994213, 2022). "In the present study, we found that SB induced cell cycle arrest at G2/M phase and reduced the protein expressions of cdc25C, CDK1, and cyclin B1 in cervical cancer cells, which may be the mechanism of action underlying the SB-inhibited cervical cancer cell proliferation." (PMID 32226384, 2020). "CDK1 binds p21 with lower affinity than Cdk2, abrogating the postmitotic checkpoint in E6-expressing cells, favoring cervical cancer development through the induction of polyploidy." (PMID 41516135, 2025). "•MiR-21-5p inhibitor enhances the radio-sensitivity of cervical cancer cells via blocking CPEB3/CDK1/Cyclin B pathway." (PMID 40746848, 2025). "In ex vivo human cervical cancer tissues, 9-oxo-ODAs decreased CDK1 expression and increased cleaved caspase 3, an apoptosis marker." (PMID 37932321, 2023). "Further mechanistic research, through bioinformatics analysis, shown that SNHG12regulates the expression of cyclin-dependent kinase 1(CDK1) through the adsorption of miR-148a to increase the radiosensitivity of cervical cancer." (PMID 35692795, 2022). "A study reported that lncRNA SNHG12 enhanced radioresistance in cervical cancer cells via miR-148a/CDK1." (PMID 35600868, 2022). "The results indicated that the induction of cell cycle arrest in cervical cancer cells is related to the MNBE mediated downregulation of CDK1, cyclin A, and B." (PMID 36088372, 2022). "CDK1, target genes of hsa_circ_0001955, have been reported to participate in cervical cancer proliferation, invasion and migration and have been associated with tumor stage and lymph node status." (PMID 34532284, 2021). "CDK1 plays a complex role in the regulation of genetic networks involved in the progression of cervical cancer." (PMID 34093198, 2021). "In cervical cancer, SNHG12 was shown to exhibit a high level, and its knockdown was observed to modulate the radiosensitivity of cervical cancer via upregulating CDK1 expression through sponging miR-148a." (PMID 34239888, 2021). "Our results showed that Drp1-knockdown in cervical cancer cells reduced the G2/M cell cycle arrest and reversed the reduction of CDK1, cyclin B1 and cdc25C expressions compared to control cells upon SB treatment." (PMID 32226384, 2020). "The results showed that SB down-regulated the expressions of CDK1, cyclin B1, and cdc25C at protein levels, which further suggests that SB induces G2/M cell cycle arrest in cervical cancer cells." (PMID 32226384, 2020). "In terms of the obtained results, the hub proteins KAT2B, PARP1, CDK1, GSK3B, WNK1, and CRYAB have been associated with several cancers in previous studies, but their association with cervical cancer is proposed here for the first time." (PMID 30020984, 2018). "In this communication we show that the knockdown of cyclin B1, the regulatory subunit of Cdk1, inhibited cell proliferation and induced apoptosis in various breast and cervical cancer cell lines." (PMID 19113992, 2008). "A previous study suggested that lower expression of hsa-miR-6705-5p was markedly correlated with the poor prognosis of cervical cancer, which could inhibit the progression of cervical cancer via targeting CDK1." (PMID 41200507, 2025). "We speculate that TCP11 gene may block the cell cycle by regulating the expression of CDK1/Cyclin B1, thereby inhibiting the proliferation of cervical cancer cells." (PMID 37697257, 2023).
cervical cancer (continued). "However, miR-148a inhibitor and CDK1 overexpression can reverse the effects of SNHG12 gene knockout on the radiosensitivity of cervical cancer cells." (PMID 35692795, 2022). "The inhibition of cervical cancer cell proliferation induced by SB may due to the increased expression of Drp1, which reduced CDK1, cyclinB1, and cdc25C expressions in G2/M cell cycle arrest." (PMID 32226384, 2020). "Prognosis of advanced stage cervical cancer may be enhanced by new therapeutics targeting CDK1 or its related pathways." (PMID 31642613, 2019). "In conclusion, these findings suggest that NCK1-AS1/miR-6857/CDK1 crosstalk serve as a critical effector in cervical cancer progression and may serve as a potential target in cervical cancer." (PMID 29416014, 2018). "The data further hint that CIP2A may be involved in the G1 checkpoint by regulating Cdk1 and Cdk2 in a B‐Myb–dependent manner in cervical cancer cells." (PMID 29893470, 2018). "Further investigation demonstrated that over-expression of MEG3 promotes apoptotic cell death and induces G2/M cell cycle arrest in cervical cancer (HeLa) and retinoblastoma (C33A) derived cell lines through the decrease of CDK1 (cyclin-dependent Kinase 1) and CCNB1 (cyclin B1) levels." (PMID 29069869, 2017). "In addition, this study also suggests that the major components of cell cycle pathway, such as CDK1/2, could be potential new targets for treating cervical cancer." (PMID 28526810, 2017). "Thus, targeting cyclin B1, leading consequently to the inactivation of Cdk1, could be a promising specific strategy for cell cycle intervention against breast and cervical cancer." (PMID 19113992, 2008). "In cervical cancer, SP1 has been shown to contribute to radioresistance through inhibiting G2/M phase arrest by targeting CDK1." (PMID 39800760, 2025). "Collectively, these data indicate that CDK1 and PLK1 represent potential therapeutic targets of GCP in the treatment of cervical cancer." (PMID 34093198, 2021). "To confirm the function of RCC1 in the cell cycle, we treated SiHa cervical cancer cells with siRCC1s and observed downregulation of E2F1, Cdk1, and Cdk2 protein levels." (PMID 29789527, 2018). "YM Cheng found that sulforaphane may dissociate the cyclin B1/CDK1 complex by up-regulating GADD45B protein, thereby arresting in the G2/M phase and inhibiting the proliferation of cervical cancer." (PMID 40855561, 2025). "Cdk1 is known as a transcriptional target of E2F1 and Sp1 proteins which is responsible for G1/S progression, and its overexpression has been stated in cervical cancer." (PMID 41516135, 2025). "It has been suggested that 9-oxo-ODAs extracted from eggplant exhibit antitumor effects by suppressing the expression of CDK1 and HPV oncoproteins, E6 and E7, in cervical cancer cells and tissues, in addition to inducing tumor-specific cell cycle arrest and apoptosis." (PMID 37932321, 2023). "Then, the top 40 hub genes were conducted to evaluate the expression and prognostic values of cervical cancer and 7 upregulated (BUB1, CCNB1, CDK1, AURKB, KIF11, PBK, NUSAP1) and 1 downregulated (ESR1) hub genes were selected to have significant values as biomarkers." (PMID 33682613, 2021). "CDK inhibitor AT7519 could suppress phosphorylation of CDK1, CDK2 and RNA polymerase II in colon and cervical cancer cells as well as overcome chemoresistance." (PMID 34112144, 2021). "After combination of the expression pattern and survival analysis, eight upregulated hub gens (CCNB1, BUB1, CDK1, AURKB, KIF11, PBK and NUSAP1) stood out with dramatical upregulation in cervical cancer and were significantly correlated with good prognosis of cervical cancer (P < 0.05)." (PMID 33682613, 2021). "Indeed, knockdown or inhibition of PLK1, CDK1, AURKA, MELK, and NEK2 resulted in reduction or repression of metastatic potential and invasiveness of various cancer types, including mCRPC and cervical cancer." (PMID 34680307, 2021).
cervical cancer (continued). "Furthermore, the KAT2B, PARP1, CDK1, GSK3B, WNK1, and CRYAB, proteins are associated with various cancer types, but their roles in cervical cancer have not been identified." (PMID 30020984, 2018).
glioblastoma (43 papers, 2008 to 2025). The most malignant astrocytic tumor (WHO grade IV). "CYCLIN A and B, which were down-regulated in NCCIT, glioblastoma and rhabdomysarcoma cells are associated with both CDK1 and CDK2, which govern the transition through G1-phase of the cell-cycle, past the restriction point." (PMID 18847459, 2008). "The CCNA1/CCNB1/CDK1/p21CIP1 pathway is associated with G2/ M-phase arrest in glioblastoma cells." (PMID 35246013, 2022). "AKAP12 phosphorylation by cyclin-dependent kinase 1 (CDK1) at a threonine residue (T766) enhances the recruitment of the polo-like kinase (PLK1) in human glioblastomas to ensure efficient mitotic progression." (PMID 36193675, 2022). "RRM2 knockdown promoted the degradation of CDK1 protein through autolysosome-dependent pathway by increasing autophagic flow, thereby inhibiting the proliferation of glioblastoma by inducing G2/M phase cell cycle arrest." (PMID 35651787, 2022). "Complete DYRK1A inhibition, as would be expected here with VER‐239353, resulted in cyclin B1 stabilization and accumulation in glioblastoma cells leading to CDK1 inhibition and cell cycle arrest." (PMID 34708541, 2021). "Treatment of glioblastoma cells with AKBA significantly decreased the ratio of p-CKD1/CDK1 and cyclin B1 suggesting that AKBA arrested the cell cycle at the G2/M phase, thereby inhibiting cell proliferation." (PMID 29970196, 2018). "CDK1 is also known to play regulatory roles in the self-renewal of mouse embryonic stem cells as well as for cell survival of glioblastoma." (PMID 26466313, 2015). "Therefore, from the data above we found that TBMS1 blocks glioblastoma cells in G2/M phase by inhibiting the expression of Cyclin A2, Cyclin B1, and CDK1." (PMID 31349699, 2019). "It has been reported that another BMI-1 inhibitor PTC596, which is efficacious in xenograft tumor models of glioblastoma, fibrosarcoma and leukemia, induces CDK1/2 binding to BMI-1 and CDK1/2-mediated phosphorylation of BMI-1 at N-terminal sites, leading to degradation of BMI-1." (PMID 31640758, 2019). "Moreover, we have previously identified LCS1269 as a potential anti-glioblastoma agent, probably interfering with cell cycle regulation through both direct CDK1 inhibition and indirect modulation of CDK1 activity through Wee1/Myt1 and FOXM1/Plk1 signaling pathways." (PMID 40649791, 2025). "Overexpression of HIC2 in glioblastoma cells (LN229 and U251) induced G2/M cell cycle arrest by down-regulating CDK1." (PMID 40650119, 2025). "Immunostaining of A-431 (human epidermoid carcinoma) and U-251MG (human glioblastoma) cell lines using the HPA003387 monoclonal antibody confirmed strong cytoplasmic and nuclear CDK1 presence." (PMID 41009727, 2025). "This study discusses our assessment of CDK1/PBK/CHEK1′s potential as theragnostic and prognostic markers in glioblastoma." (PMID 38003585, 2023). "The molecular docking results confirmed the potential of Dapagliflozin in inducing apoptosis by arresting the cell cycle by targeting CDK1, PBK, and CHEK1 in glioblastoma." (PMID 38003585, 2023). "In glioblastoma, CUDC-907 induces G1 cell cycle arrest through CDKN1A promoter hyperacetylation-driven transcriptional activation and downregulation of CDK1, while in lung fibroblast cells, CUDC-907 blocks G1 and S phase." (PMID 35205815, 2022). "MEK162 is a nonspecific CDK1 inhibitor that downregulates and dephosphorylates multiple cell cycle checkpoint proteins, including CDK1, CDK2, and Wee1382, leading to a prolonged DNA damage signal in response to IR exposure in glioblastoma cells." (PMID 32355263, 2020).
glioblastoma (continued). "It has been shown that TBMS1 reduces cyclin B1, CDK1, and AKT phosphorylation levels and elevates the level of the cKd1 inhibitor p21, which inhibits DNA synthesis and induces G2/M phase block in glioblastoma cells by targeting the PI3K/AKT/p21 and p21/CDK1/cyclin B1 signaling cascades." (PMID 40061015, 2025). "Expression levels of Cyclin-Dependent Kinase (CDK-1, CDK-2, and CDK-6) were also significantly down-regulated in U87TRAF3IP2KD cells (-9.3, -2.4, and -2.1, respectively), indicating that silencing TRAF3IP2 affects glioblastoma cell cycle progression." (PMID 30038719, 2018). "Our findings indicate that EGR3 promotes glioblastoma GBM cell growth, accompanied by increased expression of two oncogenic regulators, MYC and CDK1." (PMID 40649712, 2025). "However, the simultaneous inhibition of the chemo radio-resistant CDK1/PBK/CHEK1 oncogenic signature in glioblastoma has never been explored despite the existing cell cycle crosstalk amongst these genes." (PMID 38003585, 2023). "In good agreement with this hypothesis is a recent work showing that PI3K inhibition induces the arrest of glioblastoma cells in G2/M transition by down-regulating CDK1 and cdc25 expression without affecting the expression of cyclin B1." (PMID 23301080, 2013).
lung adenocarcinoma (41 papers, 2011 to 2026). A carcinoma that arises from the lung and is characterized by the presence of malignant glandular epithelial cells. "It has been demonstrated that aberrant activation of CDK1, a key regulator of the G2/M transition, promotes uncontrolled proliferation and resistance to apoptosis in lung adenocarcinoma." (PMID 41080754, 2025). "In conclusion, this study discovered that chrysin suppresses autophagy activation in lung adenocarcinoma cells mediated by TAMs through the regulation of the CDK1/ULK1 pathway, which reverses the growth-promoting effect of TAMs on lung adenocarcinoma." (PMID 38675475, 2024). "Under cisplatin treatment, cell cycle protein B1 and CDK1 protein levels in lung adenocarcinoma cells were significantly reduced after CCT3 knockdown." (PMID 36185198, 2022). "This phenomenon suggested that high CDK1 expression was a relevant factor for poor prognosis in lung adenocarcinoma." (PMID 36078096, 2022). "Our results suggest that the decreased expression of LINC00261 promotes the overexpression of CDK1, further promotes the occurrence of lung adenocarcinoma, and affects the prognosis of patients." (PMID 36078096, 2022). "Lung adenocarcinoma patients have a higher risk of cancer relapse and shorter recovery times, due to the elevated expression of MAD2L1 and CDK1." (PMID 36497125, 2022). "We found that overexpression of these 8 genes (CENPA, FAM83D, KNSTRN, CDKN3, CCNB1, CDK1, and CCNA2) is significantly associated with poor survival of lung adenocarcinoma patients (p-value < 0.05)." (PMID 36291764, 2022). "The prognostic value of CDK1 was further explored by clinically relevant information in lung adenocarcinoma from TCGA database, the survival package was used for statistical analysis of survival data, and the survminer package was used for visualization." (PMID 36078096, 2022). "CDK1 is overexpressed in lung adenocarcinoma and squamous cell lung carcinoma, and plays a key role in cancer progression." (PMID 35154446, 2022). "The relationship between the expression of CDK1 and tumor characteristics in patients with lung adenocarcinoma under TCGA." (PMID 34032605, 2021). "The expression level of CDK1 was correlated with pathologic T, N, M, tumor stage, and gender in the analysis of TCGA on lung adenocarcinoma." (PMID 34032605, 2021). "Integration of gene expression data from different databases (TCGA and GEO) demonstrated CDK1 upregulation in lung adenocarcinoma." (PMID 30931929, 2019). "Combined with the results of survival analysis and other comprehensive analysis, it suggested that there might be a regulatory relationship between LINC00261 and CDK1, so loss of LINC00261 in lung adenocarcinoma patients might lead to CDK1 overexpression." (PMID 36078096, 2022). "The increased expression of CCT3 in lung adenocarcinoma may lead to uncontrolled cell proliferation by promoting the expression of cyclin B1/CDK1 and thus accelerating cell cycle progression." (PMID 36185198, 2022). "On the other hand, there is a significant positive correlation between the expression of CDK1 and CXCL8 in patients with lung adenocarcinoma, suggesting that CDK1 may have a regulatory relationship with CXCL8." (PMID 36078096, 2022). "CDK1 is upregulated in lung adenocarcinoma and is suggested to have a poor prognosis." (PMID 30931929, 2019). "Aligned with the evidence above, the expression of key cell cycle regulators, like Cyclin Dependent Kinase 1 (CDK1) and Mitotic Arrest Deficient 2 (MAD2), was modulated by TRAP1 in a large cohort of colorectal, breast and lung adenocarcinoma cell lines, with consequent effects on mitotic entry." (PMID 29621137, 2018).